MSH6 (mutS homolog 6)
Diseases named in the same sentence as MSH6 in open-access papers (continued):
Sharing a sentence is not in itself a finding about the gene and the disease.
tumor (continued). "Even though none of the families carrying MSH6 variations fulfilled the AC, the variations originate from suspected LS families with MSI-H tumor phenotypes." (PMID 21120944, 2011). "Immunohistochemical staining showed MSH6 expression in all 295 non-MSI-high CRCs and in 67 out of 68 other non-MSI-high HNPCC-related tumours." (PMID 17117178, 2006). "In addition, there is functional compensation between MMR proteins (PMS2/PMS1, MSH6/MSH3), which can maintain the tumor MSS status in the absence of the four most frequently detected MMR proteins." (PMID 36591511, 2022). "Initial tumor analysis showed MSI-H and absence of MSH6 protein on IHC." (PMID 29755653, 2018). "Similar to the sellar recurrence, tumour cells were negative for MGMT and about 70% expressed MSH6." (PMID 28284009, 2017). "Even though the 11 MSH6 variations do not compose an ideal data set for the verification of the three-step model in assessing VUS pathogenicity, the importance of the interpretation of tumor IHC data prior to the identification of the VUS taken for further assessment is highlighted." (PMID 21120944, 2011).
cancer (546 papers, 1999 to 2026). A tumor composed of atypical neoplastic, often pleomorphic cells that invade other tissues. "Pathogenic variants in MSH6 have been associated with cancers other than colorectal carcinomas, including endometrial and nonmelanoma skin cancers; however, melanomas have yet to be confirmed in the tumour predisposition spectrum." (PMID 39315505, 2025). "It is known that in case of isolated loss of MSH6, MMR activity can be retained due to overlapping functions with MSH3, which explains the relatively low risk of cancer for MSH6 mutation carriers." (PMID 37190216, 2023). "A variant in MSH6 was the only variant of 14 classified in ClinVar as of “uncertain significance” that also reported a cancer-related clinical diagnosis; it was also selected as a BROCA variant and is shown later." (PMID 37046747, 2023). "Cancer genome sequencing was performed in only two patients: one patient with an MSH6 mutation and one patient with a KRAS G12V mutation." (PMID 38260832, 2023). "An integrative pan-cancer analysis show that MSH6 mutations are closely linked to the occurrence, progression or metastasis of cancer." (PMID 37035153, 2023). "Patients carrying MSH6 PVs have a cancer risk of a little less than 55% by 70 years of age and PMS2 PV carriers are at much lower cancer risk at a little less than 20% at 70 years of age." (PMID 36088367, 2022). "For MSH6, the risk is 24% for men and 40% for women while the risk of cancer development throughout life varies from 25–32% for carriers of a PMS2 mutation." (PMID 36612072, 2022).
cancer (continued). "Women with an MSH6 mutation have a 26-fold increased risk of EC and 6-fold increased risk of cancer related to LS." (PMID 35806973, 2022). "For instance, shared clonal mutations in driver genes such as ATM, ATRX, BRCA1/2, DAXX, MSH3, and MSH6 are associated with aberrations in major cellular signaling pathways like Pathways in cancer, DNA damage response, and regulation of cell cycle." (PMID 36140756, 2022). "The patient was concerned by this diagnosis and repeated MSH6 mutation testing a well-known cancer center." (PMID 33407806, 2021). "The cumulative incidences of overall cancers for MSH6 pathogenic variant carriers increase rapidly from age 50, especially for those older than 60, increasing from 18.2% (age 50) to 41.6% (age 60) in females and from 14% (age 50) to 25% (age 60) in males." (PMID 34118983, 2021). "The sisters in Family 2 demonstrate a Mendelian inheritance pattern of the two familial cancer predisposition mutations in MSH6 and BAP1." (PMID 33541411, 2021). "MSH6 mutations occurred in most cancers and were closely related to the prognosis of cancer patients." (PMID 34941572, 2021). "We found that high expression of MSH6 was linked to poor prognosis of OS for cancers of ACC, BLCA, KIRP, LGG, and SARC, while the opposite was true for KIRC and THYM." (PMID 34941572, 2021). "In this study, we provided new insights into the underlying molecular mechanisms of MSH6 in the pathogenesis or clinical prognosis of different cancers." (PMID 34941572, 2021). "That is why prospective series are still needed to precisely depict the risk of early/advanced cancer before 35 years in MSH6 and PMS2 patients." (PMID 34298719, 2021). "Although the 2-stage surgical approach was the most cost-effective strategy for individuals with MLH1 and MSH6 variants, it was associated with an increased risk of cancer compared with risk-reducing hyst-BSO at age 40 years." (PMID 34499134, 2021). "MSI-H cancer cell lines such as DLD-1 (MSH6 deficiency) and DU-145 (MLH1 and PMS2 deficiencies) cells showed a greater susceptibility to KA39 than the MSS cancer cell line HT-29, pointing out a kind of synthetic lethality." (PMID 34203761, 2021). "Patient 2 underwent genetic testing due to her known familial MSH6 mutation and family history of cancer concerning for germline BAP1 mutation." (PMID 33541411, 2021). "For example germline mutations affecting DNA repair genes, such as MSH6, have been clearly associated with a high risk of cancer development." (PMID 33541411, 2021). "For example, the expression of MSH6 gene in THCA was positively related with the cancer-associated fibroblasts’ infiltration level (cor=0.342, P=7.65e-15) based on the TIDE algorithm." (PMID 34941572, 2021). "DLD-1 cells are dMMR cancer cells bearing a missense mutation in the MSH6 gene, which is responsible for complete loss of the protein." (PMID 34203761, 2021). "Given the unique genetic architecture of the FC population of Quebec, it is likely that carriers of FANCI c.1813C>T have common ancestors as has been shown with carriers of frequently occurring pathogenic variants in BRCA1, BRCA2, and MSH6 in cancer families." (PMID 34861889, 2021).
cancer (continued). "The somatic variant MSH6 c.4001+1G>T was also identified in this patient, presumably representing the second-hit leading to biallelic inactivation typical of most cancer predisposition tumor suppressor genes." (PMID 33008098, 2020). "The cancer with unequivocal MMR defect (MSH6 loss) but MSS showed a particularly high CD8 density (958 cells/mm2)." (PMID 32108923, 2020). "Follow-up germline testing with an inherited cancer NGS panel on a peripheral blood specimen detected only the MSH6 c.10C>T (p.Gln4*) variant." (PMID 31604779, 2019). "The only meta-analysis concerning the role of MSH6 rs1042821 on cancer predisposition that we are aware of is also inconclusive." (PMID 31374908, 2019). "Despite plausible, a potential role for MSH6 rs1042821 on cancer predisposition (DTC, in particular) remains elusive." (PMID 31374908, 2019). "The MSH6 p.Leu585Pro mutation is clearly pathogenic in this study with a strong cancer risk association." (PMID 28466842, 2017). "We found four cancer-associated MSH6 point mutations extracted from the UMD and Insight/LOVD databases that map onto residues involved in pathway 2 (using a previously published alignment)." (PMID 27768684, 2016). "This is the first example of an MSH6 cancer mutation to show consequences for protein localization rather than function, an unexplored source of promoting carcinogenesis." (PMID 21437237, 2011). "A cancer-derived mutation localized between two of the three NLS significantly decreases nuclear localization of MSH6, suggesting altered protein localization can contribute to carcinogenesis." (PMID 21437237, 2011). "In the current study we report on our findings on mutation type, cancer risk and age of diagnosis in 29 families (78 participants) with a mutation in MSH6 and 6 families (7 participants) with a mutation in PMS2." (PMID 20487569, 2010).
cancer (continued). "This study reports on our findings on mutation type, cancer risk and age of diagnosis in MSH6 and PMS2 families." (PMID 20487569, 2010). "Although extra-colonic cancers, particularly endometrial, appear to be more prevalent in this group, MSH6 mutations have been implicated in the development of 22% of Amsterdam criteria-positive criteria patients with MSI-L cancers." (PMID 16106253, 2005). "Therefore, determining MSH6 variant pathogenicity is of significant clinical importance, particularly for predicting cancer risk." (PMID 40469174, 2025). "Cancer genome profiling revealed a mutation in MSH6, MS-stable status, and a high TMB of 14.5/Mb." (PMID 40530006, 2025). "Indeed, pan-cancer analyses of LS have revealed a significant prevalence of MSH6 mutations in MS-stable tumors." (PMID 40530006, 2025). "However, the molecular results revealed one case with a pathogenic MSH6 mutation along with two common cancer-driver mutations in DICER1." (PMID 39592485, 2025). "We collected multiregion WES data after MSH6 IHC from 49 LCM regions (29 MSH6-proficient and 20 MSH6-deficient regions) from 22 MMRd tumors, including 11 MMRd tumors with heterogeneous MSH6 loss, and a control group of 11 MMRd MSH6-proficient cancers." (PMID 38956208, 2024). "Those carrying pathogenic MLH1 or MSH6 variants had a cancer risk exceeding 40%." (PMID 39518119, 2024). "Moreover, female carriers of the MSH6 variant are more likely to develop or cause these cancers owing to their reduced MMR function." (PMID 38280988, 2024). "Interestingly, screening for hereditary cancer genes revealed the presence of missense mutations in DNA mismatch repair genes — MSH6 (c.2039C > T) and PMS1 (c.321A > C), whose significance has not yet been established." (PMID 37658412, 2023). "MSH6 protein downregulation may signal reduced cellular capacity to synthesize DNA repair enzymes that would otherwise protect from the accumulation of cancer-associated genetic defects." (PMID 36982970, 2023).